MTERF3 (mitochondrial transcription termination factor 3)
Description:
Binds promoter DNA and regulates initiation of transcription. Required for normal mitochondrial transcription and translation, and for normal assembly of mitochondrial respiratory complexes. Required for normal mitochondrial function (By similarity). Maintains 16S rRNA levels and functions in mitochondrial ribosome assembly by regulating the biogenesis of the 39S ribosomal subunit (By similarity).
Synonyms: MTERFD1; CGI-12; FLJ10939
Tractability: PROTAC: ubiquitination databases record sites on it; its protein half-life has been measured.
Gene: Protein-coding gene on chromosome 8 (96,238,169 to 96,261,618, reverse strand). Ensembl gene ENSG00000156469.
Subcellular location: Mitochondrion
Subcellular location (Human Protein Atlas): Mitochondria; Cytosol
Pathways (Reactome):
Metabolism of RNA: Mitochondrial mRNA modification; rRNA modification in the mitochondrion
Autophagy: PINK1-PRKN Mediated Mitophagy
Gene Ontology:
Molecular function: protein binding; transcription cis-regulatory region binding; nucleic acid binding
Biological process: negative regulation of DNA-templated transcription; mitochondrial ribosome assembly; regulation of mitochondrial transcription; regulation of DNA-templated transcription
Cellular component: mitochondrial matrix; mitochondrion; mitochondrial outer membrane
Genetic constraint (gnomAD): Loss-of-function variants: 38 observed, 41.09 expected, observed/expected ratio (o/e) 0.92, 90% interval 0.71 to 1.21. The upper end of that interval is the gene's LOEUF score, 1.21, which puts it in group 5 of 6, group 1 being the genes least tolerant of losing a copy. Missense variants: 452 observed, 499.29 expected, observed/expected ratio (o/e) 0.91, 90% interval 0.84 to 0.98. Synonymous variants: 158 observed, 175.56 expected, observed/expected ratio (o/e) 0.9, 90% interval 0.79 to 1.03.
Homologues: Orthologues: chimpanzee MTERF3 (100% identical), macaque MTERF3 (96% identical), guinea pig MTERF3 (88% identical), pig MTERF3 (86% identical), dog MTERF3 (86% identical), rabbit MTERF3 (85% identical), mouse Mterf3 (76% identical), rat Mterf3 (76% identical), tropical clawed frog MTERF3 (58% identical), zebrafish mterf3 (46% identical), Drosophila melanogaster mTerf3 (29% identical), Caenorhabditis elegans C50F4.12 (26% identical).
Diseases named in the same sentence as MTERF3 in open-access papers:
MTERF3 is named in the same sentence as 14 diseases in open-access papers, as found by Europe PMC text mining. Sharing a sentence is not in itself a finding about the gene and the disease. The quoted sentences say what the papers report.
colorectal cancer (3 papers, 2019 to 2024). A primary or metastatic malignant neoplasm that affects the colon or rectum. "MTERF3 plays an oncogenic role in colorectal cancer development by upregulating interleukin 6 and interleukin 11 to promote colorectal cancer cell growth and enhance radiotherapy resistance." (PMID 38589371, 2024). "Additionally, MTERF3 was reported to promote cell growth and irradiation resistance by regulating interleukin (IL)-6 and IL-11 in colorectal cancer cells." (PMID 38397465, 2024).
brain glioma (1 paper, 2022). A malignant glioma that involves the brain. "High MTERF3 expression correlates with cancer development and predicts a poor outcome in brain glioma patients." (PMID 36544483, 2022).
hepatocellular carcinoma (1 paper, 2024). A malignant tumor that arises from hepatocytes. "Targeting mitochondrial transcription termination factor MTERF3 induces mitochondrial dysfunction and inhibits the proliferation via activating ROS-dependent p38 MAPK pathway in hepatocellular carcinoma." (PMID 38177713, 2024).
Hyperglycemia (1 paper, 2025). An increased concentration of glucose in the blood. "Exposure to glucose at 6.5 mM (upper normoglycemia boundary) and 12 mM (validated hyperglycemia) modulated GDF15 and MTERF3 expression, highlighting a highly sensitive mitochondrial repression mechanism." (PMID 40174478, 2025). "•NR2F2 activates MTERF3 and inhibits GDF15 upon hyperglycemia." (PMID 40174478, 2025). "Understanding the interplay of NR2F2, MTERF3, and GDF15 broadens our grasp of hyperglycemia's tissue-specific impacts and may inform future therapeutic strategies targeting mitochondrial health." (PMID 40174478, 2025). "Mechanistically, MTERF3 overexpression alone recapitulated the OXPHOS inhibition but did not mimic the full hyperglycemia-induced metabolomic shifts." (PMID 40174478, 2025). "Thus, our data reveal a concerted repression of mitochondrial function in the human dermis driven by the interplay among NR2F2, MTERF3, and GDF15, offering a new perspective on hyperglycemia-induced tissue alterations." (PMID 40174478, 2025).
lung carcinoma (1 paper, 2024). "Further functional assays revealed that MTERF3 deficiency significantly attenuates the proliferation and migration ability of lung cancer cells while promoting mitophagy and the generation of mitochondrial superoxide." (PMID 38397465, 2024). "Functional studies indicated that the MTERF3 knockdown suppressed the lung cancer cell proliferation and migration, enhanced mitophagy, and increased the mitochondrial superoxide production." (PMID 38397465, 2024). "Further analysis revealed that MTERF3 knockdown significantly amplified the level of mitoSOX, a mitochondrial superoxide indicator, in lung cancer cells." (PMID 38397465, 2024). "Within the model, MTERF3 emerged as a critical regulator of lung cancer progression." (PMID 38397465, 2024). "Per its effects on mitophagy, the fluorescence labeling assay showed significant colocalization of the autophagy marker LC3 and mitochondria in lung cancer cells after MTERF3 knockdown, and the green/red (LC3/mitochondria) ratio was significantly increased in MTERF3 knockdown cells." (PMID 38397465, 2024). "Here, MTERF3 was identified as a vital MRG in our risk prediction model, and it is upregulated in lung cancer and may serve as an oncogene." (PMID 38397465, 2024).
uveal melanoma (1 paper, 2022). A melanoma derived from melanocytes of the uveal tract. "MTERF3 was substantially expressed in both high-risk and metastatic groups; hence, we hypothesized that MTERF3 may be employed as a cancer-promoting gene in uveal melanoma." (PMID 36544483, 2022).
tumor (8 papers, 2019 to 2025). "In CRC specifically, MTERF3 has been implicated in the upregulation of pro-inflammatory cytokines such as IL-6 as well as IL-11, that not only modulate tumor growth but also enhance resistance to radiotherapy." (PMID 41403952, 2025). "Additionally, MTERF3 expression was positively correlated with tumor stemness and tumor mutation burden (TMB), as well as the imputed sensitivity of doramapimod in the TCGA-LUAD dataset." (PMID 38397465, 2024). "TFB1M is involved in RNA modifications and is a crucial factor involved in type 2 diabetes and, along with MTERF3, in tumor progression." (PMID 40943143, 2025). "The results showed that MTERF3 is markedly increased in tumor tissues (P < 0.05), with 36 cases showing upregulation of MTERF3 in tumor tissue." (PMID 38177713, 2024). "In conclusion, we found that MTERF3 is frequently upregulated in HCC tumor tissues, and its higher expression positively correlated with TNM stage and poor prognosis of HCC patients." (PMID 38177713, 2024). "MTERF3 is overexpressed in HCC tumor tissues and higher expression of MTERF3 positively correlates with poor overall survival of HCC patients." (PMID 38177713, 2024). "Consistently, we enrolled 50 patients with primary HCC, and the expression of MTERF3 mRNA in tumor tissues and corresponding adjacent normal tissues were detected using quantitative real-time PCR (qRT-PCR)." (PMID 38177713, 2024). "MTERF3 is a negative regulator of mammalian mtDNA transcription and mitoribosome biogenesis in mammals and invertebrates, and the expression level of this gene is correlated with tumor progression and with sporadic cases of developmental delay." (PMID 40943143, 2025). "The results showed that MTERF3 knockdown significantly inhibited tumor growth in vivo." (PMID 38177713, 2024). "MTERF3—MTERF3 (also referred to as MTERFD1) gene amplification and high protein expression levels were present in various tumor tissues, which was correlated with a lower survival rate in patients." (PMID 33917098, 2021).
cancer (7 papers, 2022 to 2025). A tumor composed of atypical neoplastic, often pleomorphic cells that invade other tissues. "Interestingly, our findings also revealed that MTERF3 might be exploited as a cancer-promoting gene in UM, which is associated with illness advancement and poor prognosis." (PMID 36544483, 2022). "MTERF3 has been recognized as an oncogene across multiple cancer types, with gene amplification and elevated expression of MTERF3 levels strongly correlating with poor overall survival rates in cancer patients." (PMID 41403952, 2025). "In recent years, studies have found that MTERF3, as an oncogene, plays a role in various cancers and is amplified and highly expressed in many different types of cancer." (PMID 38589371, 2024). "It has been reported that MTERF3 is upregulated in several cancers including breast cancer, brain glioma and colorectal cancer, and its high expression is correlated with poor outcomes in patients with those types of cancer." (PMID 38177713, 2024). "MTERF3 gene amplification and upregulation are negatively correlated with overall survival in cancer patients." (PMID 38589371, 2024). "TCGA data showed that MTERF3 is a frequently amplified gene in several types of cancers, and the amplified frequency of MTERF3 is about 7.53% in HCC." (PMID 38177713, 2024). "Our findings indicate that the expression levels of CSNK2B, MTERF3, and PGAM5 are elevated in multiple cancers, while the expression levels of PINK1 and PRKN are reduced in several cancers." (PMID 38913914, 2024). "The MTERF family includes MTERF1, MTERF2, MTERF3, and MTERF4 that have roles in the pathogenesis of various cancer types." (PMID 38324544, 2024).
infection (1 paper, 2024). The state of being infected such as from the introduction of a foreign agent such as serum, vaccine, antigenic substance or organism. "Western blot results showed that lentivirus containing shMTERF3 infection effectively silenced MTERF3 expression in HCC-97H and LM3 cells, and MTERF3 knockdown cells displayed a weaker proliferative capacity as compared with controls." (PMID 38177713, 2024).
MTERF3 also shares sentences with these, for which no sentence is quoted: breast carcinoma (3 papers); adenocarcinoma (1); colorectal (1); dysplasia (1); ovarian carcinoma (1).